NRAS (NRAS proto-oncogene, GTPase)
Diseases named in the same sentence as NRAS in open-access papers (continued):
Sharing a sentence is not in itself a finding about the gene and the disease.
tumor (continued). "All patients entering the PROSPECT trials were tested for KRAS/NRAS mutations in the archival tumor biopsy by standard COBAS methodology, as this precluded entry into PROSPECT-C study." (PMID 33014822, 2020). "The repercussions of these distinct oncogenic properties are vast, should KRAS and NRAS mutations coexist within a heterogenous tumor." (PMID 32620824, 2020). "The limitation of this report is lacking additional genetic analysis such as looking for GNAQ, GNA11, NRAS mutations, or tumor mutation burden." (PMID 33327228, 2020). "In 5/17 (29%) cases, we observed the coincident BRAF, KRAS and NRAS mutations in cfDNA matched bone marrow tumor DNA." (PMID 32284750, 2020). "In our study, the positive BRAF, KRAS and NRAS mutations in the bone marrow tumor DNA samples were 28/83 (34%), but it was 9/17 (53%) in the plasma cfDNA samples, which demonstrated a significantly higher detection rate." (PMID 32284750, 2020). "Cell-free circulating tumor (ct) DNA was measured as either the fraction with Neuropeptide Y (NPY) methylated DNA or KRAS/NRAS/BRAF mutated ctDNA." (PMID 31731482, 2019). "KRAS/NRAS mutations are common in ICC tumours and 6–32% of patients also have isocitrate dehydrogenase 1 and 2 (IDH1 and IDH2) gene mutations associated with metabolic changes." (PMID 31795195, 2019). "As this study included only those patients who had KRAS and NRAS wild‐type disease based on tumor tissue testing, a comparison of the mutational status in tissue versus ctDNA was not plausible for these genes." (PMID 31350822, 2019). "A subclonal NRAS G13A mutation (VAF 0.03) was detected in the oligoclonal tumor arising from MYC, BCL2, P53dd transduced cells." (PMID 31586074, 2019). "KRAS and NRAS tumour mutational status are required for anti-EGFR mAbs prescription since the presence of mutations in exons 2, 3 or 4 of these genes have extensively been described as predictive marker of treatment resistance." (PMID 31265477, 2019). "BRAF and NRAS mutations were mutually exclusive except for the single tumor harboring the BRAF V600R mutation, which was also NRAS c61 mutant." (PMID 30672666, 2019). "The initial mutational status (i.e., mutations in BRAF, NRAS) of the primary tumor was recovered in CTC and ctDNA in 47.6–70.6% of all cases." (PMID 31671846, 2019). "Sixteen of 25 plasma samples had detectable level of KRAS (n = 14), BRAF (n = 1) or NRAS (n = 1) mutations, which were 100% concordant to reported tumour DNA genotype." (PMID 30585255, 2019). "Patients with gene mutations in the tumor had a shorter survival time than patients with the wild type gene, except for NRAS, BRAF, and EGFR mutations." (PMID 31255173, 2019). "The results of this study showed that KRAS and NRAS mutataions are usually present in the large majority of tumor cells, whereas BRAF and PIK3CA mutations often affect a limited, subclonal fraction of tumor cells." (PMID 29652830, 2018). "NRAS mutations were identified in 12 out of 353 (3.4%) tumor samples, with 5 cases in exon 2 (1.4%) and 7 cases in exon 3 (2.0%)." (PMID 29666387, 2018). "We show that impairing mitochondrial function and blunting the ROS-scavenging machinery renders NRAS-mutant tumor cells susceptible to excessive ROS levels, leading to tumor cell death." (PMID 29695835, 2018). "When BRAF and NRAS mutation were analysed separately, patients with BRAF mutant tumours compared to patients with BRAF/NRAS wild-type tumours had increased risk of developing disease recurrence following a negative SLNB (aHR 2.07, 95% CI 1.05–4.09, p = 0.04)." (PMID 29755118, 2018). "The genetic profile of HT-29 cells represents the KRAS and NRAS wild-type tumor subtype, but includes the activating V600E mutation in the BRAF gene." (PMID 30410004, 2018).
tumor (continued). "There were 477 patients in the MMP cohort who underwent SLNB and had BRAF/NRAS mutation testing of their tumour from 2010–2015." (PMID 29755118, 2018). "There was some evidence to suggest that patients with NRAS mutant tumours compared to those with BRAF/NRAS wild-type tumours had an increased risk of developing disease recurrence following a negative SLNB (aHR = 1.72, 95% CI 0.80–3.67, p = 0.16)." (PMID 29755118, 2018). "Usp9x depletion blocked expansive tumour growth in matrigel, particularly in tumours with NRAS mutations." (PMID 28198367, 2017). "Many other cancer types also show NRAS mutation with an important clinical impact on the overall population in view of tumor incidence, mortality and survival." (PMID 28522871, 2017). "The variants of p.G12V and p.G12C as two hotspot mutations of the NRAS exon 1 were found only in 3 out of 34 tumours." (PMID 28900470, 2017). "Polysomy of chromosome 1 and intra-tumour NRAS/chromosome 1 heterozygosity were frequently found in our series and was preferentially observed in NRAS mutated cancers." (PMID 28668077, 2017). "Of the 11 SpTs in which FGFR3/HRAS/NRAS mutations have been identified so far, chromosomal copy number information is available for only one tumor (SS2) from an 84 year old man." (PMID 28542371, 2017). "Another study finds that the mutation of NRAS is related to the suppression of apoptosis in tumor development." (PMID 29513198, 2017). "Comparing melanoma tumours collected before BRAF inhibitor therapy to resistant tumours in the same patient after therapy identified acquired NRAS mutations in many of these tumours, including in tumours that continue to harbor the BRAF mutations." (PMID 28282860, 2017). "Prevalence of BRAF and NRAS mutations, immune infiltration and PD-L1 expression in the tumor samples obtained pre-treatment were classified according to response." (PMID 29157311, 2017). "Local relapse at the primary tumor site was rare and observed in only 6 patients (2.8%), 4 of whom showed NRAS mutations." (PMID 28797232, 2017). "First, different murine and human tumor cells sharing codon 61 NRAS mutations presented uniform pulmonary tropism independent from coexisting mutations and tissue of origin." (PMID 28341702, 2017). "Activation of the oncogenic RAS pathway by the NRAS mutation suppresses the immune response by decreasing expression of major histocompatibility complex on tumor-cell surfaces and recruitment of regulatory T lymphocytes." (PMID 28107203, 2017). "Secondly, we analyzed chromosome 1 microsatellite polymorphism in normal and tumor DNA in a group of 29 NRAS mutated cancers by ALFP method." (PMID 28668077, 2017). "Polysomy was mainly observed in NRAS mutated tumours and disomic and/or disomic but rare polysomic cells were less frequent in High non-HET M%NRAS than in M%NRAS WT tumours." (PMID 28668077, 2017). "The median age at detection of brain metastasis was 56.0 years in BRAF mutated tumours, 59.5 years in NRAS mutated tumours and 69.5 years in BRAF wild-type tumours." (PMID 27213536, 2016). "The median age at detection of brain metastasis was 56.0 years in BRAF mutated tumours (range 35–71 years), 59.5 years in NRAS mutated tumours (range 35–76 years) and 69.5 years in BRAF wild-type tumours (range 40–75 years)." (PMID 27213536, 2016). "A tumor sample with a new mutation of exon 59 of NRAS oncogene (as present in exon 59 of KRAS oncogene) would therefore produce a low correlation coefficient, allowing the operator to detect this unusual sample." (PMID 27651826, 2016). "Three members of the GTPases of the RAS family, KRAS, HRAS and NRAS, are well known for their ability to cause neoplasia." (PMID 27857191, 2016).
tumor (continued). "Of the 14 cases, 8/14 (57 %) exhibited KRAS (exon 2, codon 12 or 13) mutations in the primary tumour and 1/14 (7 %) a NRAS (exon 3, codon 61) mutation." (PMID 27756406, 2016). "Multiple KRAS and NRAS codon 12 and 13 microclonal mutations significantly co-occurred within tumor samples (p=4.8×10−4), suggesting ongoing formation of and selection for Ras-activating mutations." (PMID 27683039, 2016). "One subject with a low NRAS G12C mutant allele frequency (5%) did show a 50% tumor reduction after cetuximab treatment." (PMID 26989027, 2016). "It has been shown that patients with tumor mutations in KRAS exon 2 as well as KRAS exons 3 or 4 or NRAS exon 2, 3, or 4 are likely to show resistance to anti-EGFR agents." (PMID 26452027, 2015). "For instance, concurrent NRAS and MEK1 mutations or even two different NRAS mutations have previously been identified to be present within the same tumour on progression." (PMID 26174485, 2015). "NRAS mutations were found in 82 (22%) tumor samples, including 37 (45%) Q61R, 25 (25%) Q61K, 14 (17%) Q61L, 4 (5%) Q61H and 2 (1%) G12D mutations." (PMID 26327518, 2015). "BRAF mutant allele frequencies were highly concordant with the KRAS and NRAS mutant allele frequencies, suggesting that concomitant mutations are present in the same tumor population." (PMID 26498038, 2015). "Whereas targeting mutant KRAS remained difficult, several studies demonstrated that NRAS mutations can be targeted by inhibition of MEK in tumor cell lines." (PMID 26544513, 2015). "To investigate the significance of MAPK-mediated upregulation of hnRNP K in radioresistance of MM, we analyzed the effects of IR in a MM cellular tumor model carrying an activating NRAS p.Q61L mutation (IPC-298)." (PMID 26136337, 2015). "The histological tumor type in all patients whose tumor tissue contained NRAS mutations was the diffuse type of adenocarcinoma." (PMID 24774510, 2014). "As described, all 13 whole genome analyzed cases harbored mutations or copy number alterations in either NRAS or BRAF (with 1 tumor having both)." (PMID 25393105, 2014). "Patients whose tumor tissue contained a NRAS codon 12/13 mutation had a significantly shorter OS compared with those carrying the NRAS wild type (8.8 month vs. 14.7 months, p = 0.011, log-rank test)." (PMID 24774510, 2014). "We observed that most of the tumor samples (~80%) had more than 25% of NRAS mutant alleles, corresponding to more than 50% of the cells carrying a NRAS heterozygous mutation." (PMID 25254041, 2014). "BRAF/NRAS wild-type tumours were also found to have a higher average mutation rate compared to BRAF/NRAS mutant tumours." (PMID 24752294, 2014). "In this paper, we described the development and analytical validation of a custom designed, multiplexed mutation assay to detect 35 mutations of interest in KRAS, BRAF, and NRAS genes in FFPE tumor tissue for patient stratification in clinical trials." (PMID 23991070, 2013). "The two tumours that presented a BRAF or NRAS mutation also presented the ATF1-EWS fusion gene and were considered atypical." (PMID 22693489, 2012). "The NRAS mutation findings are particularly interesting from the perspective of tumor heterogeneity." (PMID 22235286, 2012). "PIK3CA, HRAS and AKT1 (all n = 1) mutations were detected in FFPE tumor specimens, while NRAS, PIK3CA and AKT1 (all n = 1) mutations were found in cpDNA samples." (PMID 23144797, 2012). "Only one tumor had two mutations (NRAS Q61L and CTNNB1 45P), while all other mutations were mutually exclusive." (PMID 22536370, 2012). "No oncogenic BRAF mutations were identified in exon 11 in any of the tumour biopsies evaluated, and only one oncogenic NRAS (61K) mutation was detected." (PMID 16880785, 2006). "Of three RAS genes found to be activated by mutation in human tumours, NRAS (neuroblastoma RAS viral (v-ras) oncogene homologue) is most commonly mutated in cutaneous melanomas." (PMID 15928660, 2005).
tumor (continued). "In addition to genetic mutations such as BRAF^V600E^ and NRAS, lipid metabolic reprogramming has emerged as a critical factor in tumor progression and therapy resistance." (PMID 41596686, 2026). "Interestingly, complete concordance for hotspot driver mutations, such as BRAF V600 and NRAS Q61K, between tumor and ctDNA samples occurred even at low SNV burdens, with individual VAFs ranging from 0.2% to 28%." (PMID 39859576, 2025). "Since at the time of diagnosis, only tumour DNA was profiled by Sanger sequencing, we first aimed to determine whether the NRAS mutation was somatic or germline." (PMID 41168392, 2025). "All tumours with Class I mutations exhibited concomitant BRAF or NRAS mutations." (PMID 40107205, 2025). "However, this study was limited to only four patients and, in general, mutations in NF1 or NRAS in NB tumours occur rarely." (PMID 41511287, 2025). "KRAS or NRAS were mutated in six tumours (16%), and IDH1 or IDH2 were mutated in 5 tumours (14%)." (PMID 38877653, 2024). "NRAS and KRAS mutations share phenotypic traits, such as promoting tumorigenicity, but certain NRAS variants like Q61K can enhance tumor proliferation, while others like G12D might reduce proliferation and increase apoptosis." (PMID 39684219, 2024). "Additionally, we didn’t have all the molecular tumor characteristics such as NRAS and BRAF mutations, which also affect the response to anti-EGFR antibody therapy." (PMID 39202071, 2024). "Interestingly, we also observed significant enrichment and associations for NRAS or KRAS within tumor types such as blood, lymphoid, and ovary." (PMID 39455841, 2024). "Similarly to activating mutations in KRAS, their counterparts in NRAS also speed up tumor progression." (PMID 39456660, 2024). "In the first case, a 13-year-old presented with PCI of 16 and neoadjuvant chemotherapy-responsive disease and proceeded to CRS and HIPEC plus ultrasound ablation of hepatic capsule implants, followed by adjuvant trametinib and chemotherapy for an oncogenic NRAS mutation on tumor sequencing." (PMID 37345152, 2023). "In addition, two variants of uncertain biologic significance were discovered in KIT (missense, p.K492R) and HRAS (nonsense, p.Q70*) as passenger mutations in a tumour (case 22M) with a concomitant NRAS mutation." (PMID 36416305, 2023). "Previous studies of biomarkers in tumor tissues have shown that the mutation status of genes known to be associated with CRC carcinogenesis (NRAS, KRAS, and BRAF) and defects in the DNA mismatch repair system, exert substantial effects on the treatment decision." (PMID 36394150, 2023). "From a biological standpoint, it is worth noting that both BRAF and NRAS mutations are present in nevi, suggesting that such mutations might represent early events that could already be present in all tumor cells." (PMID 38003476, 2023). "Furthermore, changes in NRAS variant allele frequency in ctDNA were highly correlated with changes in tumor size, which is partly in line with a previous study." (PMID 36600247, 2023). "The mutational status of these tumours was also accessible for TERTp, NRAS, and BRAF genes." (PMID 37568724, 2023). "With this in mind, our study aimed to evaluate the frequency of RAS mutations (including both KRAS and NRAS) and to investigate a possible association between these mutations and certain clinicopathological characteristics, as well as tumor localization, in a group of Bulgarian patients with mCRC." (PMID 37628934, 2023).
tumor (continued). "In our cohort, the molecular evaluation of RAS mutational status in tumor tissue samples, performed by NGS, confirmed a low frequency of both KRAS and NRAS mutations in mCRC patients, which is in agreement with the data reported in the literature for this type of tumor (1–5% for mCRC)." (PMID 37296579, 2023). "NRAS mutation was significantly associated with tumor location, especially the extremities." (PMID 34110110, 2022). "Additionally, CRC patients with KRAS and NRAS mutations have less favorable prognoses, shorter survival, and increased tumor aggressiveness." (PMID 35723313, 2022). "We pinpoint the dLED characteristic of the NRAS gene, meaning that if a tumor has NRAS mutated a treatment that targets NRAS itself would be the best option to reduce their tumorigenicity, whereas if it is NRAS wild-type, a PTPN11 inhibition would be a better recommendation." (PMID 35805023, 2022). "WES identified KRAS, BRAF, and NRAS mutations in a total of 27 tumours (93%)." (PMID 35715628, 2022). "Therefore, the identification of the most deleterious single nucleotide polymorphisms (SNPs) in the NRAS gene is necessary to understand the key factors of tumor pathogenesis and therapy." (PMID 36051694, 2022). "NRAS total mutations were identified in 3.2% (35/1090) tumor samples." (PMID 36344948, 2022). "The variant allele frequencies (VAFs) of the PIK3CA and NRAS mutations were relatively low (median, 6%; range, 1–38%), compatible with relatively low histopathologic estimated percentage of tumor nuclei (%TN) to overall cellular nuclei (median, 20%; range, 10–70%)." (PMID 35787784, 2022). "There is an association between her GCT and ALL, as the two malignancies may share a common clonal origin and the NRAS mutation likely plays a role in tumor genesis." (PMID 36547180, 2022). "Because FTCs or PTC cases harboring NRAS or KRAS mutations exhibit the maximum tumour shrinkage, the tumour genotype may represent a predictor of response to cabozantinib." (PMID 35408830, 2022). "However, the WES analysis of KRAS and NRAS mutations in AT-1 and AT-2 suggests that both serial sister cell lines consist of two clones from the primary tumor." (PMID 34940123, 2021). "NRAS mutations were identified in 6 (2.9%) out of 210 tumor samples." (PMID 33784337, 2021). "Furthermore, NRAS mutation in primary tumors proved to be an independent factor of tumor progression." (PMID 34209415, 2021). "Moreover, an NRAS mutation became evident in another part of this tumor after using a specific antibody for this mutation." (PMID 34072863, 2021). "Interestingly, NRAS mutation of the primary tumor was present only in 6.9% of SLN-positive tumors, while it was detected in 20.8% of SLN-negative cases; however, this difference was not statistically significant either." (PMID 34209415, 2021). "Similarly, a close related oncogene, NRAS whose mutation status was found to significantly associated with the predicted sensitivity to trametinib for three tumor types." (PMID 33858332, 2021). "As a result, all patients entering the PROSPECT-R trial had a cataloged KRAS/NRAS variant that could be used to investigate the tumor content of the respective biopsy samples." (PMID 33014822, 2020). "Importantly, the MITF‐low/proliferative subtype, characterised by an absence of the expression of immune‐response genes, had only BRAF/NRAS‐mutated samples and more tumours with CDKN2A deletions, and was significantly associated with a poorer prognosis." (PMID 30511391, 2019). "KRAS, NRAS or BRAF mutations had been identified in tumour samples from sixteen of the twenty-four patients (75%), and in twelve of these (75%) the mutation could be verified in the pre-treatment plasma sample by ddPCR." (PMID 31395942, 2019).